ZP3 (zona pellucida glycoprotein 3)
Diseases named in the same sentence as ZP3 in open-access papers (continued):
Sharing a sentence is not in itself a finding about the gene and the disease.
cancer (continued). "We noticed that an alternative ZP3 RNA transcript, which we term ‘ZP3-Cancer’, was annotated in gene databases that lacks the genetic information encoding the N-terminal signal peptide that governs entry into the secretory pathway." (PMID 38125942, 2023). "To obtain further insight into the cancer related expression of ZP3-Cancer, we analyzed publicly available, transcript-level RNAseq data for tumor tissues of the TCGA (10386 tumor tissues)." (PMID 38125942, 2023). "Analysis of publicly available RNA-sequencing data of CCLs, tumor tissues and healthy tissues revealed that this alternative ZP3 mRNA transcript, which we term ZP3-Cancer, is dominantly expressed in tumor cells and highly enriched in various types of cancer." (PMID 38125942, 2023). "Our ZP3 transcript-focused analysis of the same data cohorts strongly suggests that ZP3-Cancer dominates the cancer-enriched signature." (PMID 38125942, 2023). "In the present study, we aimed to broaden our view of the cellular localization pattern of ZP3 by investigating protein expression in different types of cancer." (PMID 38125942, 2023). "IHC data for several cancer types showed abundant ZP3 protein staining, which was confined to the cytoplasm, contradicting the extracellular protein localization in oocytes." (PMID 38125942, 2023). "In this study we describe the expression of a novel ZP3 mRNA transcript in cancer cells that is different from the ZP3 transcript expressed in oocytes." (PMID 38125942, 2023). "Among these cancer-types with enriched expression, the ZP3-Cancer expression level varied considerably." (PMID 38125942, 2023). "The proof-of-principle for the development of a ZP3-based cancer vaccine for active immunization has been demonstrated in a transgenic mouse model of ovarian granulosa cell cancer." (PMID 38125942, 2023). "This classifies ZP3-Cancer largely as a tumor specific antigen and renders it a potential tumor marker and attractive immunotherapeutic target for the treatment of cancer." (PMID 38125942, 2023). "Although ZP3 expression has been found in 100% of normal tissue, it has also been present in 64% of OSCC samples which leads to an exclusion of ZP3 for a good potential cancer-specific biomarker." (PMID 35330493, 2022). "Altogether, our data indicates that ZP3-Cancer may be involved in supporting tumor cell survival and aggressive behavior." (PMID 38125942, 2023). "Expression of ZP3-Cancer in tumor cells was confirmed by qPCR." (PMID 38125942, 2023). "In addition to the expression in female and male gametes under physiological circumstances, ectopic expression of ZP3 has been shown in cancer." (PMID 38125942, 2023). "In tumor tissues, ZP3-Cancer is also clearly the dominant protein-coding transcript." (PMID 38125942, 2023). "Next, we investigated whether ZP3-Cancer was differentially expressed across the different cancer types covered by the CCLs." (PMID 38125942, 2023). "The publicly available RNAseq data of CCLs and tumor tissues, and our independent computational and qPCR analysis, provide a clear explanation for the cytoplasmic localization of ZP3 observed in cancer, as these data show that ZP3-Cancer is the dominant transcript in tumor cells." (PMID 38125942, 2023). "We performed a ZP3 transcript specific analysis of publicly available RNA-sequencing (RNA-seq) data of cancer cell lines (CCLs) and tumor and normal tissues, and validated expression data by independent computational analysis and real-time quantitative PCR (qPCR)." (PMID 38125942, 2023). "Localization of ZP3 to the plasma membrane of tumor cells may be observed, as RNAseq analysis identified the ZP3-Oocyte transcript in cancer, but only in a very limited number of cases." (PMID 38125942, 2023).
cancer (continued). "The first exon of the ZP3-Cancer transcript is located approximately 27 kilobase pairs upstream of its second exon, which largely overlaps with the first exon of the ZP3-Oocyte transcript, suggesting that a different transcription activation mechanism regulates ZP3-Cancer expression." (PMID 38125942, 2023). "While the enriched expression of ZP3 in cancer versus normal tissue provides a therapeutic opportunity, whether ZP3 is secreted from cancer cells or not is an important strategic determinant for the development of a cancer immunotherapy based on active or passive immunization." (PMID 38125942, 2023). "The other two protein-coding ZP3 transcripts that encode putative cytoplasmic proteins, ZP3-203 and ZP3-204, are expressed at very low levels in tumor cells, and are therefore unlikely to contribute to the cytoplasmic levels of ZP3 protein in cancer." (PMID 38125942, 2023). "In this respect, the near absence of the ZP3-Cancer transcript (or the other protein-coding ZP3 transcripts) in healthy tissue is corroborated by recently published ZP3 IHC data for 14 different healthy human tissues and organs, showing the absence of protein expression." (PMID 38125942, 2023). "As we found significant relationships between ZP3-Cancer transcript levels and OS, DSS and PFI in KIRC, the overlap in these data between the two studies may be explained by ZP3-Cancer being the dominant transcript of the gene-level ZP3 expression level in KIRC tumors." (PMID 38125942, 2023).
tumor (2 papers, 2022 to 2023). "The identification of ZP3-Cancer as an alternative ZP3 transcript that encodes a protein localized to the cytoplasm of tumor cells, will spark research into its ectopic function." (PMID 38125942, 2023). "To find an explanation for the differential cellular localization of ZP3 in oocytes and tumor cells, we took a closer look at the ZP3 mRNA isoforms annotated in the NCBI Genbank and Gencode/Ensembl databases." (PMID 38125942, 2023). "Publicly available RNAseq data for the seven annotated ZP3 RNA transcripts of 1339 CCLs was analyzed to obtain insight into their expression level in tumor cells." (PMID 38125942, 2023). "Next, we investigated whether ZP3-Cancer is selectively enriched in tumor cells relative to healthy tissue." (PMID 38125942, 2023). "Localization of ZP3 protein in tumor cells appeared nearly exclusively cytoplasmic." (PMID 38125942, 2023). "This explains the intracellular localization of ZP3 in tumor cells." (PMID 38125942, 2023). "The findings from these different studies raised the question whether tumor cells produce an alternative ZP3 protein compared to that expressed in oocytes." (PMID 38125942, 2023). "Therefore, we decided to compare ZP3-Cancer expression in tumor tissue to that in healthy tissue." (PMID 38125942, 2023). "In addition, expression of the transcription factor that activates ZP3 expression in developing oocytes, FIGLA, was found to be virtually absent in CCLs (n=1355) and tumor tissues (n=11133) (median expression of 0.0 in both sample cohorts, data not shown)." (PMID 38125942, 2023).
infection (1 paper, 2024). The state of being infected such as from the introduction of a foreign agent such as serum, vaccine, antigenic substance or organism. "The results show that ZP3 could only infect Xoo strains, suggesting infection specificity towards this species." (PMID 39339926, 2024).
ZP3 also shares sentences with these, for which no sentence is quoted: anovulation (1 paper); diabetic retinopathy (1); embryonal carcinoma (1); esophageal adenocarcinoma (1); glioma (1); granulosa cell tumor (1); head and neck squamous cell carcinoma (1); Huntington disease (1); kidney tumor (1); lung adenocarcinoma (1); lung carcinoma (1); ovarian adenocarcinoma (1); ovarian granulosa cell tumor (1); ovarian tumors (1); pancreatic ductal adenocarcinoma (1); prostate adenocarcinoma (1); prostate tumor (1); triple-negative breast carcinoma (1); uterine corpus endometrial carcinoma (1).